XRN1 (5'-3' exoribonuclease 1)
Diseases named in the same sentence as XRN1 in open-access papers (continued):
Sharing a sentence is not in itself a finding about the gene and the disease.
infection (continued). "We found that infections with RNA viruses from different families, including NDV, EMCV, Sendai virus (SeV), and vesicular stomatitis virus (VSV), trigger the aggregation of XRN1 and DCPs into distinct subcellular compartments containing viral ribonucleoproteins." (PMID 32034313, 2020). "Inhibition of NFκB activity through pharmacological inhibitors (i.e., TPCA-1 and BAY 11-7082) did not affect XRN1-DCP1a-mediated antiviral activities and XRN1 aggregation upon infection with CVB3, a positive ssRNA virus." (PMID 32034313, 2020). "Further analysis revealed that infection with Adeno-5 or HSV-1 failed to stimulate cytoplasmic aggregation of XRN1 and DCP1a." (PMID 32034313, 2020). "The fact that knockdown of Xrn1 or Dis3L2 does not rescue Pol II occupancy during WT MHV68 infection indicates that either these mechanisms are redundant, or that the Pol II depletion phenotype is dominant." (PMID 32032393, 2020). "Upon infection, it reduces the cytosolic levels of Xrn1, Pan3, and Dcp1a, but no GW182 in a time-dependent manner." (PMID 31681621, 2019). "We hypothesized that prior infection with ZIKV could be confirmed through the presence of subgenomic flavivirus RNA (sfRNA) of the 3′ untranslated region (UTR), which persists in tissues due to XRN-1 stalling during RNA decay." (PMID 33863991, 2021). "Notably, we observed that infection with Adeno-5 and HSV-1, two nuclear-replicating DNA viruses, fails to trigger XRN1-DCPs aggregation, and that viral replication remains comparable when DCP1 and XRN1 were depleted in IFN-I-deprived cells." (PMID 32034313, 2020). "However, Xrn1 resistance does not appear to be as robust as in the MBFVs and serves a somewhat different purpose in that it does not result in accumulation of a noncoding RNA that alters multiple host pathways during infection." (PMID 29317714, 2018). "The A549 cells lacking the XRN1 protein showed increased IFN-β, IFIT1, IFIT3, and ISG15 expression compared with the A549 control cells at 4 to 8 h after WSN infection." (PMID 34311580, 2021). "It is also known that depletion of RNA decay factors like XRN1 and UPF1 doesn’t have any effect on infection of negative stranded RNA viruses of the Paramyxoviridae and Bunyaviridae families." (PMID 29494679, 2018).
cancer (10 papers, 2016 to 2025). A tumor composed of atypical neoplastic, often pleomorphic cells that invade other tissues. "XRN1 has recently been implicated as a cancer target whose disruption potentiates the effect of cancer immunotherapy via a mitochondrial antiviral-signaling protein-dependent mechanism." (PMID 40804482, 2025). "Because dysregulated gene expression is a critical driver of cancer, XRN1 may be closely associated with cancer progression by degrading specific RNAs that are important for maintaining normal cellular status." (PMID 38689093, 2024). "Taken together, this comprehensively accumulated evidence in various organisms supports the idea that XRN1 is a significant miRNA-modulating factor in human diseases, especially cancer." (PMID 38689093, 2024). "Recent studies targeting XRN1 in cancer cell lines have shown that depletion of XRN1 can induce a viral mimicry phenotype in cancer cells." (PMID 39221819, 2024). "Several lines of evidence support XRN1 as a key player in cancers based on its intrinsic exoribonuclease activity." (PMID 38689093, 2024). "The metabolic implications of targeting XRN1 should be explored in relation to immunotherapy, considering that targeting nucleotide metabolism could enhance cancer immunotherapy." (PMID 40804482, 2025). "The exonuclease XRN1 has recently been identified as a novel target for cancer immunotherapy." (PMID 39757707, 2025). "For instance, some cancer cells become dependent on adenosine‐to‐inosine (A‐to‐I) editing of IR‐Alus by the deaminase ADAR1, compromising the double‐stranded structure of Alu elements, while other cancer cells become dependent on IR‐Alu dsRNA decay by the exonuclease XRN1." (PMID 39592415, 2025). "Besides XRN1, cdc42 is another miR-204 target which has a dual yet opposite growth-regulatory function in cancer cells." (PMID 27438705, 2016). "Furthermore, targeting its intrinsic RNA cleavage activity could be a potential therapeutic strategy for XRN1-dysregulated cancers by simultaneously regulating both its target mRNAs and miRNAs." (PMID 38689093, 2024). "While ADAR1, XRN1 and DDX3X are essential only in some cancer cell lines, DHX9 is more commonly essential across all cancer cell lines." (PMID 39221819, 2024). "However, the miRNA-modulating effects of XRN1 in various cancers have not been comprehensively reviewed yet." (PMID 38689093, 2024).
tumor (7 papers, 2015 to 2025). "5′–3′ exonuclease XRN1 is an enzyme being involved in conventional RNA decay, which is also implicated in cancer as a tumour suppressor." (PMID 31572192, 2019). "For instance, XRN1, a 5′–3′ exoribonuclease, was found to affect the turnover of several tumor-suppressive miRNAs beyond the conventional miRNA degradation mechanism by forming complexes with other factors such as IFIT515." (PMID 38689093, 2024). "Among these target genes, the expression of BDNF, MEIS1, FOXC1, NUAK1, RAB22A, and XRN1 is inversely correlated with that of miR-204 in those tumor specimens examined, strongly suggesting that miR-204 is one of the key suppressors of the target genes." (PMID 27438705, 2016). "Nevertheless, our results so far support that XRN1 may repress recurrence via its tumor suppressive activity in NEPC cells." (PMID 25797256, 2015). "Moreover, since CD44 knockdown represses Akt phosphorylation and growth of PC-3 cells, inhibition of CD44 expression by XRN1 is likely critical for XRN1 tumor suppressive function in NEPC cells." (PMID 25797256, 2015). "In contrast to its tumor suppressive role in PAC cells, miR-204, by targeting XRN1, functions as an oncomiR in NEPC cells." (PMID 25797256, 2015). "Finally, it should be noted that down-regulation of miR-34a by XRN1 might contribute to PCa progression independent of AR, since miR-34a can act as a tumor suppressor through directly inhibiting CD44 in tumorigenic and metastatic PCa stem cells." (PMID 25797256, 2015).
metabolic disorders (1 paper, 2024). "And another study also, like our results, showed that the lack of association between XRN1 and YTHDC2 in the hypothalamus may contribute to metabolic disorders." (PMID 38453794, 2024).
XRN1 also shares sentences with these, for which no sentence is quoted: prostate adenocarcinoma (2 papers); asthma (1); breast carcinoma (1); endometrial carcinoma (1); melanoma (1); prion disease (1); Telangiectasia (1).